U3 (Small nucleolar RNA U3 )
Synonyms: LOC124906377
Gene: Small nucleolar RNA gene on chromosome 3 (30,304,321 to 30,304,536, reverse strand). Ensembl gene ENSG00000281710.
Gene Ontology:
Biological process: RNA processing
Cellular component: nucleolus
Homologues: Orthologues: chimpanzee U3 (99% identical), macaque U3 (82% identical), dog U3 (76% identical), dog U3 (75% identical), dog U3 (73% identical), rabbit U3 (60% identical), rat LOC120098417 (31% identical), dog U3 (30% identical). Paralogues in human: SNORD3G (81% identical), SNORD3P1 (80% identical), SNORD3E (79% identical), U3 (78% identical), SNORD3D (77% identical), U3 (77% identical), SNORD3H (76% identical), U3 (75% identical), U3 (74% identical), U3 (73% identical), U3 (72% identical), U3 (71% identical), and 9 more.